NCOR1 (nuclear receptor corepressor 1)
Diseases named in the same sentence as NCOR1 in open-access papers (continued):
Sharing a sentence is not in itself a finding about the gene and the disease.
cancer (continued). "Of these, NCOR1, MUC4, and MUC16 genes have been investigated for their aberrant expression in various cancers and being attractive targets for immunotherapy in previous studies." (PMID 33504001, 2021). "For example, the expression of corepressors such as NCOR1 and NCOR2/SMRT determine how several cancers respond to nutritive ligands." (PMID 31683867, 2019). "Taken together, these data suggest that CIM7 and inhibition of the NCoR1/RARα interaction may have therapeutic potential beyond NSCLC, with broader pan-cancer applications." (PMID 40490560, 2025). "Brain-derived neurotrophic factor (BDNF), a growth factor with relevance in several cancer types, was also found strongly to be induced in the absence of NCOR1." (PMID 34503224, 2021). "Cell cycle, cancer and cell morphology are the top functions influenced by genes in Network A. Sixteen genes differentially expressed between NC and CIN III are involved in this network including RBL2/p130, SMARCC1, NCOR1, PTEN, DHFR and CDKN2B." (PMID 18248679, 2008). "Moreover, several TFs play known roles in cancers, such as ASCL1, NCOR1, SMAD2, and SMAD4." (PMID 39716176, 2024). "The precise molecular mechanisms underlying HDAC4's role in cancer remain incompletely understood, but it may involve interactions with the corepressor complex NCOR1/NCOR2/HDAC3 and influence the transcription landscape of cancer cells through epigenomic reprogramming." (PMID 38911380, 2024). "However, to date, this NCoR1/RARα-dependent regulation of CMA has not been established in cancer cells, nor has it been determined whether it can impact tumor growth." (PMID 40490560, 2025). "To examine whether in cancer cells, the corepressor complex could mediate the activation function of REV-ERBα, we knocked down NCoR1 and NCoR2 and found that their knockdown did not cause any significant effect on the expression of REV-ERBα activated genes in PI3K and MAPK signaling programs." (PMID 39383000, 2024). "When grouping cancer genes into canonical cancer pathways, mutations in the SWI–SNF complex (for example, SMARCA4, ARID1B and SMARCB1) and certain members of the NOTCH signalling pathway (for example, EP300 and NCOR1) were under significant subclonal, but not truncal, selection in LUAD." (PMID 37046096, 2023). "We also showed that disrupting the specific interaction of NCoR1/RARα leads to selective inhibition of CMA, without contribution of macroautophagy, and that this inhibition of CMA in cancer cells can be attained without major changes to CMA in normal cells." (PMID 40490560, 2025). "Additionally, analysis of gene expression in NSCLC cancer patients revealed a significant increase in both CMA score and NCoR1/RARα ratio in tumor tissue compared to non-tumorigenic lung tissue (Fig. EV7A,B)." (PMID 40490560, 2025). "In the absence of agonist, LXRA but not LXRB, is primarily repressed by corepressors NCOR1 and NCOR2/SMRT and previous reports demonstrate elevated corepressor expression helps prostate and bladder cancer cells to evade anti-proliferative actions of NRs through compromising the ligand response." (PMID 31683867, 2019).
tumor (74 papers, 2007 to 2025). "Among these genes, PDE4D, LRP1B, CREBBP, and NCOR1 were previously associated with deletions in BC tumor tissue, which favors tumorigenesis or progression." (PMID 40801146, 2025). "This miRNA downregulates the tumor‐suppressive nuclear receptor co‐repressor NCOR1, developing a greater tumor volume and causing decreased survival in orthotopic xenografts." (PMID 36300592, 2023). "The mutation NCOR1 c.2182G>C (p.Val728Leu) was identified as a somatic mutation in the tumor sample of patient P6." (PMID 33058520, 2020). "The results showed that NCOR1 was abnormally down-regulated in tumor tissues than paired normal tissues, and was associated with tumor stage advance." (PMID 31661545, 2019). "We also noticed that the NCOR1 gene product in the PanTT39 tumour harboured a mutation at position 120 (R120L)." (PMID 30377343, 2019). "Young TILs produced 327 pg IFN-γ/10e5 TILs in response to mutated NCOR1, while tumour cell-stimulated TILs showed 710 pg IFN-γ/10e5 TIL." (PMID 30377343, 2019). "In addition to prolonged OS after treatment with ICIs, NCOR1 mutations were associated with higher tumor immunogenicity, activated antitumor immunity, a number of mutations in the DDR pathway, immune cells and upregulated expression of immune-related genes." (PMID 33763074, 2021). "Based on the NCOR1 mutation status, we explored possible factors that may affect the difference in immunotherapy efficacy in tumor patients." (PMID 33763074, 2021). "We evaluated that whether DLK1 and NCOR1 co-expression in nucleus is associated with any tumor character, the answer of which might give a hint on the mechanism of how DLK1 affects Notch signaling pathway." (PMID 31661545, 2019). "We found one sub-network of genes around NCOR1 which might be an example of other tumor suppressor genes that are affected by the concerted loss of these genomic loci." (PMID 20052266, 2010). "Genomic profiling revealed EGFR and JUN amplifications with NCOR1 and PRKAR1A losses, alterations linked to aggressive tumor biology." (PMID 40979503, 2025). "Next, we sought to evaluate the capacity of CIM7 to inhibit CMA and reduce NSCLC tumor growth in vivo as well as the translational potential to inhibit CMA via NCoR1/RARα targeting in NSCLC." (PMID 40490560, 2025). "Organoid lines also exhibited somatic mutations in RCC‐related genes which were in concordant with respective tumor including ESPL1, SMARCB1, RAB21, NCOR1, NLRC5, NOTCH2, and FOXA2 mutations." (PMID 38923304, 2024). "Thirdly, NCoR1 was highly phosphorylated in tumor tissues, in line with the enhanced PAK4 protein levels." (PMID 37591884, 2023). "Among the four mutated genes (i.e., NCOR1, MUC16, MUC4, and RSPO2), NCOR1, MUC16, and MUC4 were reported to have been directly involved in modulating tumor microenvironment and thereby mediating drug resistance." (PMID 33504001, 2021). "Downregulation of NCOR1 in these cells drastically impaired the capacity of HT-29 cells to form tumors under these conditions, with a coincident reduction in tumor weight at the time of mouse sacrifice compared to the control HT-29 cells." (PMID 34503224, 2021). "Our observations highlight the complexity of targeting senescence as an overall tumor suppression strategy, but open up possibilities for future studies to manipulate NCOR1 at different disease stages in a program designed to treat colon tumorigenesis." (PMID 34503224, 2021).
tumor (continued). "In the TCGA-BLCA-cohort, compared with NCOR1-WT, NCOR1-MT was associated with known predictors of ICB therapy efficacy, such as higher tumor mutational burden (TMB), neoantigen load and the number of mutations in the DNA damage-repair pathway." (PMID 33763074, 2021). "As a consequence of NCOR1 decreased expression, the tumor suppressive activity of MAD1 is decreased and myeloid differentiation is impaired." (PMID 32024211, 2020). "RT‐PCR confirmed the abnormal mRNA splicing on the NCOR1 exon 19 in the patient's tumor, suggesting NCOR1 c.2182G>C (p.Val728Leu) to be likely oncogenic." (PMID 33058520, 2020). "The PML-RARα fusion protein is not only a misfolded protein by itself, but also promotes aberrant folding of nuclear receptor corepressor 1 (NCOR1), a protein essential for the function of several tumor suppressors, including Max dimerization protein 1 (MAD1)." (PMID 32024211, 2020). "From DN negative samples to DN positive samples, with the emergence of DLK1 and NCOR1 in the nucleus, the proportion of early tumor samples (stage I) significantly increased (P=0.013)." (PMID 31661545, 2019). "We analyzed the expression of NCOR1 in two independent cohorts and demonstrated that NCOR1 is a tumor suppressor and has prognosis potential in lung squamous carcinomas." (PMID 31661545, 2019). "The expression level of NCOR1 was reduced in tumor compared with normal, and the LUSC samples seemed to have smaller median value than the LUAD samples." (PMID 31661545, 2019). "We investigated the correlation of NCOR1 expression and the clinical features of the samples, including patients’ age, gender, tumor histological type, tumor stage, tumor size, node metastasis status and cell differentiation degree." (PMID 31661545, 2019). "In LUAD, the NCOR1 expression was raised accompanied with the advancement of pathologic T stage, which mainly stands for larger tumor size." (PMID 31661545, 2019). "Since we performed the IHC of NCOR1 and DLK1 on the same batch of samples, we investigated the co-location of DLK1 and NCOR1 in tumor cells." (PMID 31661545, 2019). "Studies have shown that interfering NCOR1 expression can enhance cell proliferation and invasion, which leads to tumor growth and metastasis." (PMID 31661545, 2019). "With the appearance of DLK1 and NCOR1 in the nucleus, the proportion of early tumor stage increased, and the proportion of large tumor size decreased." (PMID 31661545, 2019). "Consistent with our results, NCOR1 is down-regulated in tumor samples and has a prognosis potential in LUSC." (PMID 31661545, 2019). "We do not yet fully understand this observation, but one possibility is that tumor cells with high NCoR1 levels and repressed mitochondrial activity already grow at their metabolic limit." (PMID 26832397, 2016). "Overall, 22.6% of tumours harboured a coding mutation in one of the seven Mut-driver genes involved in chromatin function (KMT2C, ARID1A, NCOR1, CTCF, KDM6A, PRBM1 and TBL1XR1)." (PMID 27161491, 2016). "We have previously shown that Nuclear Receptor Corepressor 1 (NCoR) and the thyroid hormone receptor β1 (TRβ) inhibit tumor invasion." (PMID 27806339, 2016). "To test whether JUN’s ability to restrain tumor growth depends on NCOR1/2 expression, we cloned mirE-based tandem shRNA constructs targeting NCOR1 and NCOR2 into the myr-AKT-HA vector." (PMID 39210147, 2024). "Notably, combinatorial treatment with tamoxifen and TNFα or sh-NCOR1 decreased the tumor volumes more consistently than TNFα or sh-NCOR1 treatment alone." (PMID 34073371, 2021).
tumor (continued). "Although our results support that abrogation of NCOR1 function could be beneficial as a tumor suppressor strategy in CRC cells, our findings also point to the promotion of metastatic potential in the same context." (PMID 34503224, 2021). "Interestingly, the tumor volume was reduced by tamoxifen as well as TNFα treatment or NCOR1 knockdown." (PMID 34073371, 2021). "Similarly, the results of the ESTIMATE algorithm suggested that NCOR1-MT tumors have a higher immune score [370 (−290–1,200) versus −120 (−650–580); P < 0.01) and tumor purity [460 (−1400–1600) versus −810 (−2,100–620); P < 0.05]." (PMID 33763074, 2021). "Also, 22 variants in five genes [ICOSLG, NCOR1, KMT2C, HLA-A and AR] were found to be pathogenic/ likely pathogenic in other tumor types." (PMID 33075099, 2020). "A novel NCOR1 c.2182G>C (p.Val728Leu) was identified in tumor." (PMID 33058520, 2020). "Given the importance of Siah2 in the regulation of mitochondrial metabolism and its tumor‐promoting role, it is worth mentioning that the NCoR1/HDAC3 repressor complex also controls cell proliferation via its role in cell cycle regulation and DNA repair pathways." (PMID 26832397, 2016). "We show one example of a sub-network around the nuclear co-repressor NCOR1 that may be a novel network of tumor suppressor genes that are affected by the observed co-occurring losses." (PMID 20052266, 2010). "Additionally, several mutations not previously reported in OSCC sequencing studies were detected in 7% of cases including mutations in ARID1A (chromatin remodeling), BIRC6 (apoptosis inhibition), DCC (neural regulation and tumor suppression), and NCOR1 (transcriptional inhibition)." (PMID 41154345, 2025). "Moreover, we observed specific TNFα-induced apoptosis of ERα-positive cells, consistently with our previous report, and we further confirmed that knockdown of NCOR1 and TNFα treatment exerted a similar targeted apoptosis-inducing effect in vitro and tumor growth inhibition in vivo." (PMID 34073371, 2021). "Our findings demonstrate upregulation of the NCoR1/RARα axis and elevated CMA activity in NCSLC tumor tissue and cell lines." (PMID 40490560, 2025). "Co-occurring CN loss and hypomethylation events were more prevalent in LUSC, affecting TSGs including NCOR1 (29 of 59 tumor regions), CDKN2C (28 of 59 tumor regions), CREBBP (26 of 59 tumor regions) and RPL22 (9 of 59 tumor regions)." (PMID 40931149, 2025). "Specifically, PIWIL4, SATB1, GSE1, NCOR1, SAP30L, ATM, and BMI1 were significantly downregulated in tumor tissues relative to normal controls, while BUB1, CHEK1, MASTL, DNAJC2, UBE2D1, and SSRP1 showed pronounced upregulation." (PMID 41208974, 2025).
tumor (continued). "Both NCOR1 and NCOR2/SMRT were expressed at significantly lower levels in ER-negative tumours compared to ER-positive tumours (two-tailed Mann–Whitney U test: p < 0.001)." (PMID 31683867, 2019). "The expression of NCOR1 was dramatically reduced in advanced tumor samples (stages III and IV) compared with early stage tumor samples." (PMID 31661545, 2019). "Copy losses were also commonly observed for key tumor suppressors relevant to mCRPC biology, including GRHL2, ZFHX3, FGFR2, NCOR1, PHLPP1, and BRCA1." (PMID 31136607, 2019). "In a panel of 39 NSCLC tumor tissues and 10 non-tumorigenic lung tissues from human patients, we found significantly higher levels of NCoR1 nuclear protein levels in NSCLC tumors, while nuclear protein levels of RARα were comparable between the two groups." (PMID 40490560, 2025). "In this study, mutations in the genes ARID1A, APC, ERBB4, NCOR1, PDGFRA, ATM, and CDKN2A were either non-recurrent or of very low frequency, while none of the 14 sequenced EP tumours harboured mutations in the genes HRAS, EGFR, or RB1." (PMID 34045664, 2022). "In terms of tumor stage and size, DLK1 and NCOR1 showed a synergistic effect in nucleus." (PMID 31661545, 2019). "This confirms the role of NCOR1 as a tumor suppressor gene in the estrogen receptor negative tumors." (PMID 30485330, 2018). "In human OS, NCOR1 was amplified in 22.6% of tumors where it did not correlate with disease free interval, and amplification status correlated significantly with tumor size." (PMID 19735553, 2009). "Furthermore, immunostaining for the cell proliferation marker Ki67 also showed that NCOR1 knockdown selectively inhibited tumor cell proliferation in MCF7 but not MDA-MB-231 xenograft mice." (PMID 34073371, 2021). "Tumor growth of HT-29 cells was reduced in the absence of NCOR1 in the mouse xenografts." (PMID 34503224, 2021). "In LUSC, the negative correlation between NCOR1 expression and tumor stage was revealed." (PMID 31661545, 2019). "In their BC study, Zhang and colleagues observed lower NCOR1 mRNA expression with higher histological grade, negative ERα and PR statuses, but positive HER2 status and a tumor diameter larger than 2 cm." (PMID 39696035, 2024). "In this article, we now elucidate a negative feedback mechanism in which high YAP activity is restrained by the recruitment of JUN/NCOR1 repressor complexes and show that this non-canonical JUN function is part of a tumor suppressor mechanism in the liver." (PMID 39210147, 2024). "Consistent with animal studies, immunoblotting analysis of liver tissues obtained from HCC patients indicated higher levels of PAK4, total-, phospho-, and nuclear-NCoR1, and lower levels of HMGCS2 in tumor compared to non-tumorous tissues." (PMID 37591884, 2023). "Interestingly, tumor weight was significantly reduced in the xenograft mouse model inoculated with NCOR1-silenced MCF7 cells (p < 0.001), whereas NCOR1 knockdown did not significantly reduce tumor weight in MDA-MB-231 xenograft mice." (PMID 34073371, 2021).